CD4 (CD4 molecule)
Diseases named in the same sentence as CD4 in open-access papers (continued):
Sharing a sentence is not in itself a finding about the gene and the disease.
acute kidney injury (36 papers, 2013 to 2025). Sudden and sustained deterioration of the kidney function characterized by decreased glomerular filtration rate, increased serum creatinine or oliguria. "A strong association between the presence of CD4– T cell populations and the high risk of progression to renal failure was identified." (PMID 35775489, 2022). "Therefore, we conclude that high B cell densities are associated with a good prognosis, while high densities of CD4– T cells are associated with progression to renal failure." (PMID 35608910, 2022). "It remains to be determined whether a specific CD4– T cell population is associated with progression to renal failure or if these populations share pathogenic roles." (PMID 35608910, 2022). "PLWH who died were older than 50 years old, females, smokers, had acute kidney injury, CD4 less than 200 mm3, hypoxemic, high CRP, and HbA1c." (PMID 36855103, 2023). "hAECs motivate the expression of miR-101 in CD4+ T cells in acute kidney injury (AKI) patients that inhibit the activation of CD4+ T cells." (PMID 35337387, 2022). "Rather, it is CD4– T cell populations, including CD8+, γδ, and other DN T cells, that are associated with refractory disease and progression to renal failure." (PMID 35608910, 2022). "Compared with CD8+ T cell, CD4+ T cell is a more important mediator of ischaemic acute renal failure." (PMID 34102079, 2021). "Exploratory analysis demonstrated lower CD4 and higher total CD8 proportions, higher anti-BKPyV antibody titers and the cause of renal failure were associated BKPyV reactivation." (PMID 28562595, 2017). "We conclude that mainly CD4+ T-cells and APCs in the advanced phase play a direct and critical role in the immune response to the pathological mechanism in LPS-induced acute kidney injury." (PMID 29261164, 2017). "Additionally, in a mouse model of sepsis-associated acute kidney injury (SAKI), HUCMSC-Exos deliver miR-375 to CD4+ T cells, thereby alleviating AKI in SAKI mice by promoting autophagy and inhibiting T cell apoptosis." (PMID 40746857, 2025). "Orai1 promotes lymphocyte IL17 expression in CD4+ cells and, in turn, contributes to acute kidney injury (AKI) and AKI-to-CKD progression." (PMID 34764278, 2021). "Another role for IL-33 was demonstrated by Akcay and colleagues, finding that IL-33 promotes acute kidney injury (AKI), through CD4 T cell-mediated production of the pro-inflammatory chemokine CXCL1." (PMID 30769901, 2019). "In addition, IL-33 promotes acute kidney injury through CD4 T cell-mediated production of CXCL1." (PMID 27579324, 2016). "Acute kidney injury (AKI) is a common complication in ambulatory HIV-infected patients treated with HAART and has been associated with prior renal impairment, lower CD4 levels, AIDS, hepatitis C virus coinfection and liver disease." (PMID 23394360, 2013). "In summary, our results demonstrated that IL-18Rα-mediated signaling plays critical roles in CD4+ T-cells and APCs and was markedly faster at responding to IFN-γ and IL-18 than TLR4 stimulation in the pathogenesis of LPS-induced acute kidney injury." (PMID 29261164, 2017). "Among the patients who developed ESRD, there was a small subset who were already in renal failure at the time of biopsy, and those patients had fewer B cells and a more apparent increase of CD4– T cells compared with patients who were not in renal failure." (PMID 35775489, 2022). "In the pathophysiology of acute kidney injury (AKI), hypoxia-inducible factor (HIF-1α) is expressed in renal tubular cells and can increase the secretion of IL-22 through the activation of CD4+ T cells, thereby regulating glucose metabolism and increasing glycogen storage." (PMID 35432360, 2022).
gastritis (36 papers, 2008 to 2026). Inflammation of the stomach. "The authors showed in mice that Peyer’s patches (PPs) in the small intestine are indispensable for H. pylori antigen-specific priming of naïve CD4+ T-cells, which then home to the stomach and subsequently cause gastritis." (PMID 38343887, 2024). "The division of the CD4+/CD3+ ratio in the gastric body by the CD4+/CD3+ ratio in the gastric antrum (body CD4+/antrum CD4+) revealed a significantly higher value in cases of autoimmune gastritis compared with H. pylori-associated gastritis." (PMID 37504250, 2023). "Receiver-operating characteristic analysis demonstrated the superior effectiveness of antrum CD8+/CD4+ in distinguishing autoimmune gastritis from H. pylori-associated gastritis, as compared with body CD4+/antrum CD4+." (PMID 37504250, 2023). "The gastritis in these thymectomized mice is caused by parietal cell specific CD4+ T cells infiltrating the gastric mucosa and initiating disease, followed by autoreactive B cells producing anti-parietal cell antibodies." (PMID 34900999, 2021). "HpaA specific CD4+ T cell responses were mainly observed in patients with gastritis, the mildest gastric disease associated with H. pylori infection, representing that HpaA specific CD4+ T cell response was protective." (PMID 27509059, 2016). "H. pylori-induced gastritis is associated with recruitment of Treg cells into the antral mucosa, suggesting a putative role for this CD4+ T cell subset in both the persistence of H. pylori infection, and in modulating systemic inflammation." (PMID 23166823, 2012). "CD4+ T cells from H/Kα−/− mice caused gastritis in irradiated wildtype mice suggesting that this population is more pathogenic than CD4+ T cells from H/Kβ−/− mice." (PMID 22096532, 2011). "Similarly, dividing the CD8+/CD3+ ratio by the CD4+/CD3+ ratio in the gastric antrum (antrum CD8+/CD4+) yielded a higher value for autoimmune gastritis than for H. pylori-associated gastritis." (PMID 37504250, 2023). "Therefore, it is reasonable to believe that CD4+ lymphocytes are increased in both the body and antrum samples in H. pylori-associated gastritis, whereas they are increased in the body samples alone in autoimmune gastritis." (PMID 35735608, 2022). "CD4+ lymphocytes are reported to be mediators of inflammation in H. pylori-associated gastritis." (PMID 35735608, 2022). "However, the pathogenic CD4+ T cell subset involved in gastritis and the potential regulators are still unclear." (PMID 34589088, 2021). "Further comparisons showed that the percentage of HpaA specific CD4+ T cells in the gastritis group was significantly higher than that in the peptic ulcer group, indicating that the strength of HpaA specific CD4+ T cells was associated with gastric disease potentially caused by H. pylori infection." (PMID 27509059, 2016). "It is also suggested that the number of CD4+ lymphocytes in the gastric body mucosa is larger than that in the antrum mucosa in autoimmune gastritis, whereas the gastric body and antrum are evenly affected by CD4+ lymphocyte infiltration in H. pylori-associated gastritis." (PMID 35735608, 2022). "Esophagogastroduodenoscopy showed severe acute gastritis, and biopsy specimens demonstrated infiltration of CD4+ lymphocytes into the stroma and CD8+ lymphocytes into both the epithelium and stroma, as well as IgA deposition along interstitial capillaries." (PMID 40792275, 2025). "Few of these reports describe the reasoning and/or mechanisms behind the gastritis; however the most notable findings include the predominance of CD4+ and CD8+ T lymphocytes." (PMID 41330429, 2025). "This roseolovirus-induced gastritis was found to rely on replication during the neonatal period as well as CD4+ T cells and IL-17." (PMID 37504250, 2023). "Antrum CD8+/CD4+ in autoimmune gastritis (7.86 ± 7.23) was also higher than that in active (1.49 ± 0.58) and inactive gastritis (2.84 ± 2.17)." (PMID 35735608, 2022).
gastritis (continued). "Lymphocytes of the lesser curvature of the body showed that the CD4+/CD3+ ratio was higher in the active gastritis group than in the inactive gastritis group (66.1 ± 12.8% vs. 43.8 ± 19.4%)." (PMID 35735608, 2022). "Comprehensive flow cytometry analysis of autoimmune, active, and inactive gastritis revealed that the lymphocyte composition differed in CD4+/CD3+ and CD8+/CD3+ ratios." (PMID 35735608, 2022). "A comparison of the lymphocytes in the greater curvature of the antrum samples between the groups revealed that the CD4+/CD3+ ratio was lower in autoimmune gastritis group members than that in the active gastritis group (19.7 ± 13.1% vs. 47.5 ± 13.5%)." (PMID 35735608, 2022). "We identified a class of TFH-like CD4+ T cells with the capacity to secrete IL-21 in the gastric mucosa of H. pylori-positive gastritis patients and demonstrated that the GITR/GITRL axis promoted IL-21+CD4+ T cell polarization via the STAT3 signal pathway." (PMID 34589088, 2021). "Collectively, our findings expand the understanding of IL-21+TFH-like CD4+ T cells in H. pylori-positive gastritis and investigate the underlying regulatory mechanism, which may provide potential interventions in the clinical treatment of H. pylori-induced gastritis." (PMID 34589088, 2021). "Gastric CD4+T cells contribute to Helicobacter pylori (H. pylori)-induced gastritis by amplifying mucosal inflammation and exacerbating mucosal injuries." (PMID 34589088, 2021). "We demonstrated that the culture supernatant of CD4+T cell from H. pylori-positive gastritis patients promoted MMP3 and MMP9 secretion of GES-1 cells." (PMID 34589088, 2021). "Data showed that the percentage of IL-21+CD4+T cells was positively correlated with the frequency of B cells in the mucosa of H. pylori-positive gastritis patients." (PMID 34589088, 2021). "The results showed that the co-localization of IL-21 with CD4+ T cells in the gastric mucosa was increased in H. pylori-positive gastritis patients." (PMID 34589088, 2021). "Meanwhile, a positive correlation was also observed between the percentage of GITR+CD4+T cells and B cell frequency in the gastric mucosa of gastritis patients." (PMID 34589088, 2021). "The results showed that B cells co-cultured with CD4+T cells from H. pylori-positive gastritis patients had a higher ratio of proliferation compared to those co-cultured with CD4+T cells from healthy controls." (PMID 34589088, 2021). "Meanwhile, we identified glucocorticoid-induced tumor necrosis factor receptor (GITR) as an important regulator to facilitate IL-21 production by CD4+T cells and accelerate mucosal inflammation in gastritis patients with H. pylori infection." (PMID 34589088, 2021). "Consistent with the increased percentage of IL-21-producing TFH-like cells, the expression of GITR was also elevated in mucosal CD4+T cells from H. pylori-positive gastritis patients." (PMID 34589088, 2021). "In this study, we explored the expression and function of CD103 in mucosal resident CD4+T cells from patients with H. pylori-positive gastritis." (PMID 32974219, 2020). "In this study, we found that CD103 was highly expressed in CD4+T cells of the gastric mucosa from patients with H. pylori-positive gastritis." (PMID 32974219, 2020). "Flow cytometry data showed that CD103 was highly expressed in gastric CD4+ T cells from H. pylori-positive gastritis compared to with that in the normal control." (PMID 32974219, 2020). "Together, these results demonstrated that CD103+CD4+ T cells were increased in the gastric mucosa of patients with H. pylori-positive gastritis." (PMID 32974219, 2020). "CD4+ T cells have been shown to be increased in H. pylori gastritis, but gastric inflammation has been shown to correlate with lower H. pylori bacterial load, and pro-inflammatory genetic profiles are associated to lower H. pylori seroprevalence." (PMID 26599971, 2015).
gastritis (continued). "The gastritis in mice is characterized by the infiltration of CD4+ T cells, B cells, neutrophils, mast cells and eosinophils that secrete cytokines or mediators, presumably making the environment unfavourable for the colonization of H. pylori." (PMID 26168305, 2015). "There is a limited mechanistic understanding regarding the contributions of CD4+ T cell subsets to gastritis development during H. pylori colonization." (PMID 24039925, 2013). "In contrast, mice that received wildtype CD4+ T cells were completely free of gastritis, which indicated that autoimmune gastritis in mice receiving H/Kα−/− CD4+ T cells was not caused by irradiation per se, but rather, the T cell inoculum." (PMID 22096532, 2011). "The ratio of FoxP3+ Treg cells to total CD4+ T cells was significantly lower in gastritis lesions (12.6±1.7%, n = 5) than in the spleen (19.0±3.8%, n = 3; P<0.01)." (PMID 18716662, 2008). "Adoptive transfer experiments suggest that autoimmune CD4+ T cells mediate gastritis development as terminal effector cells." (PMID 18716662, 2008). "CD4+ T cells are known to mediate vaccine-induced protection, and it has previously been reported that populations of Treg cells that are usually prevalent in H. pylori gastritis are reduced in vaccinated mice." (PMID 40869057, 2025). "An analysis combining the lymphocyte composition of the antrum with that of the body revealed that the body CD8+/antrum CD8+ ratio was not different between the groups, whereas the body CD4+/antrum CD4+ ratio in autoimmune gastritis was higher than that in active and inactive gastritis." (PMID 35735608, 2022). "Taking these data together, we revealed that GITR/GITRL signal promoted the polarization of mucosal IL-21-producing CD4+T cells in H. pylori-positive gastritis, which may provide therapeutic strategies for the clinical treatment of H. pylori-induced gastritis." (PMID 34589088, 2021). "In addition, an increased percentage of IL-21+ CD4+T cells was detected in biopsy samples from H. pylori-positive gastritis patients." (PMID 34589088, 2021). "Furthermore, the blockage of IL-21 in the co-culture system inhibited B cell proliferation induced by CD4+T cells from H. pylori-positive gastritis patients." (PMID 34589088, 2021). "In this model, the transgenic CD4+ T cells initiate disease progression which follows the same pattern seen in humans: gastritis progressing to atrophic gastritis by 2 months of age, metaplasia by 4 months of age, and then mice begin to show signs of gastric dysplasia by 12 months of age." (PMID 34900999, 2021). "Our results explore the function of CD103 in gastric CD4+T cell of H. pylori-positive patients, which may provide a therapeutic target for the treatment of gastritis." (PMID 32974219, 2020). "However, in spite of a strong influx of CD4+ T cells, B cells, eosinophils, mast cells and dendritic cells in the stomach of vaccinated mice post-challenge which manifests as severe gastritis, the infection is rarely eradicated." (PMID 26168305, 2015). "Therefore, CD4+ T cells are necessary and sufficient for gastritis induction in the H. pylori infection model." (PMID 24039925, 2013). "The area under the receiver operating characteristic (ROC) curve of body CD4+/antrum CD4+ was 0.799, and that of antrum CD8+/CD4+ was 0.842, indicating that the latter formula was superior to the former for the identification of autoimmune gastritis versus active or inactive gastritis." (PMID 35735608, 2022). "In superficial and atrophic gastritis, the types of factors and chemokines correlated with central memory CD4 T cell were quite different, which indicated that the chemokines and interleukins recruiting immune cells to the inflammatory tissue varied with the severity of gastritis." (PMID 33426088, 2020).
gastritis (continued). "The accumulation of H. pylori-specific CD4+ T cells observed in infected human gastric mucosa suggests that CD4+ T-cell-mediated Th1 immune responses may be critical in the development of H. pylori-induced gastritis." (PMID 22526791, 2012). "Similarly, the gastritis that spontaneously develops in AID−/− mice at later stages could be reconstituted in nu/nu mice by adoptive transfer of CD4+ T cells." (PMID 18716662, 2008). "Antrum CD8+/CD4+ of autoimmune gastritis (7.86 ± 7.23), calculated by dividing CD8+/CD3+ by CD4+/CD3+ in the greater curvature of the antrum, was also higher than that of active (1.49 ± 0.58) and inactive gastritis (2.84 ± 2.17)." (PMID 35735608, 2022). "Here we identified an IL-21-producing gastric CD4+T cell subset, which exhibited tissue-resident CXCR5−BTLA−PD-1hi TFH-like phenotype in H. pylori-positive gastritis patients." (PMID 34589088, 2021). "We firstly analyzed the percentage of gastric CD19+B cells as well as the correlation between the percentage of IL-21+CD4+T cells and CD19+B cells in H. pylori-positive gastritis patients." (PMID 34589088, 2021). "Taking these data together, we found that IL-21+ CD4+T cells were increased and exhibited TFH-like phenotype in H. pylori-positive gastritis patients compared to healthy controls." (PMID 34589088, 2021). "Therefore, a large number of central memory CD4 T cells could be found in gastritis." (PMID 33426088, 2020). "T-bet (T-box expressed in T cells) is a transcription factor that is required for differentiation of T CD4+ cells and their secretion of IFN-γ and hence holds a central role in the development of gastritis due to H. pylori." (PMID 26525279, 2015). "H. pylori-specific CD4+ T-cells, together with prolonged IFNγ secretion, were shown to be indispensable for gastritis, as mice lacking either H. pylori-specific CD4+ T-cells or IFNγ did not develop gastric inflammation." (PMID 38343887, 2024). "Body CD4+/antrum CD4+, which is calculated by dividing the CD4+/CD3+ ratio in the body by that in the antrum, was significantly higher in autoimmune gastritis (3.54 ± 3.13) than in active (1.47 ± 0.41) and inactive gastritis (1.42 ± 0.77)." (PMID 35735608, 2022). "In conclusion, our study showed that CD4+/CD3+ and CD8+/CD3+ ratios in the greater curvature of the gastric antrum and the lesser curvature of the body were different in autoimmune, active, and inactive gastritis." (PMID 35735608, 2022). "Moreover, GITR expression was increased in gastric CD4+T cells of gastritis patients compared to healthy controls, along with the upregulated expression of its ligand GITRL in mucosal macrophages (Mφ) of gastritis patients." (PMID 34589088, 2021). "We speculate that the affected area of the stomach caused the difference in antrum CD8+/CD4+, rather than body CD8+/CD4+, between the gastritis types." (PMID 35735608, 2022). "Body CD4+/antrum CD4+, which is calculated by dividing CD4+/CD3+ in the lesser curvature of the body by CD4+/CD3+ in the greater curvature of the antrum, was significantly higher in autoimmune gastritis (3.54 ± 3.13) than in active (1.47 ± 0.41) and inactive gastritis (1.42 ± 0.77)." (PMID 35735608, 2022). "Furthermore, CD3+ T cells from Cre+ mice transferred the lethal wasting disease into congenic wild-type (WT) recipients, with expansion and activation of donor CD4+ and CD8+ T cells, gastritis and expression of messenger RNA for proinflammatory mediators in the stomach." (PMID 28931816, 2017). "Our results suggest that the post-immunization gastritis of sublingually immunized mice may be promoted by CD3+CD4- derived IFN-γ (and possibly other pro-inflammatory cytokines), whereas CD3+CD4+ derived IL-17A appears to be specific to the anti-bacterial response to H. pylori infection." (PMID 26168305, 2015).
gastritis (continued). "Furthermore, gastric CD4+ T cells recovered from BALB/cnu/nu mice produced significant quantities of IL-17 or IFN-γ but not IL-4, suggesting that Th1 and/or Th17 cells function as terminal effectors of gastritis development in AID−/− mice." (PMID 18716662, 2008). "These mice did no longer show gastritis and immune infiltration in lacrimal and salivary glands as observed in Malt-PD mice, nor did they show an increase in IFN-γ producing CD4+ T cells." (PMID 31474984, 2019). "Three months later, mice that received CD4+, but not CD8+, T cells developed gastritis characterized by a massive infiltration of Mac1+ cells, epithelial hyperplasia and reduction of gastric glands." (PMID 18716662, 2008).